HDAC9 (histone deacetylase 9)
Diseases named in the same sentence as HDAC9 in open-access papers (continued):
Sharing a sentence is not in itself a finding about the gene and the disease.
preeclampsia (3 papers, 2021 to 2025). Preeclampsia is a hypertensive disorder of pregnancy that is characterized by new-onset hypertension with proteinuria presenting after 20 weeks of gestation, and depending on mild or severe forms may initially present with severe headache, visual disturbances, and hyperreflexia. "Recent findings indicate placental HDAC9 is diminished in preeclampsia, and a loss of HDAC9 deters placental trophoblast cell migration and invasion via hyperacetylation of the tissue inhibitor of metalloproteinases 3 (TIMP3) promoter, increasing TIMP3 levels." (PMID 41416997, 2025). "This hypothesis, along with other suggested regulators of HDAC9 in preeclampsia, will be discussed in the subsection titled GPCR-Associated Kinases and Oxidative Stress as Potential Drivers of HDAC9 Dysregulation in Preeclampsia." (PMID 41416997, 2025). "This review focuses specifically on the IIa subgroup, with a particular emphasis on HDAC9, due to its emerging relevance in the placenta during preeclampsia." (PMID 41416997, 2025). "The link between GPCR activation and attenuated HDAC9 in preeclampsia is further discussed in the subsection titled GPCR-Associated Kinases and Oxidative Stress as Potential Drivers of HDAC9 Dysregulation in Preeclampsia." (PMID 41416997, 2025). "In summary, preeclampsia is a multidimensional disorder consisting of placental, vascular, and immune dysfunction, and recent research suggests that HDAC9 is a significant molecular contributor." (PMID 41416997, 2025). "Currently, our knowledge of HDAC9 in preeclampsia is restricted to ex vivo human placental tissues, in vitro cell culture experiments, and data extrapolated from related disease states." (PMID 41416997, 2025). "Class II HDACs have been shown to promote MMP9 expression in primary amnion cells, but the specific relationship between HDAC9 and other MMPs in preeclampsia has yet to be elucidated." (PMID 41416997, 2025). "In preeclampsia, HDAC9 was downregulated, and knockdown of HDAC9 upregulated the expression of TIMP3 in HTR‐8/SVneo cells." (PMID 34262394, 2021). "Therefore, the purpose of this review is to synthesize the available literature applicable to placental HDAC9 in preeclampsia, with the aim of informing future research and therapeutic strategies." (PMID 41416997, 2025). "While HDAC9 is down-regulated in syncytiotrophoblasts during preeclampsia, its role in decidual macrophages over the course of gestation remains unclear and warrants further investigation." (PMID 41416997, 2025). "However, this review only begins to dissect some of the known and putative targets of HDAC9 relevant to preeclampsia, with a vast number likely still undiscovered." (PMID 41416997, 2025). "Notably, no existing studies directly assess the precise role of HDAC9 in placental development across gestation or its involvement in the presentation of systemic features of preeclampsia, with maternal HDAC9 expression also remaining unexplored." (PMID 41416997, 2025). "Of the many HDACs, HDAC9 is particularly intriguing in the context of preeclampsia due to its decreased presence in preeclamptic placenta and prominent role in controlling trophoblast, vascular, and immune behavior, which are often dysregulated in this condition." (PMID 41416997, 2025). "Though HDAC9 has not been directly linked to this process, HDAC9 is localized to the syncytiotrophoblast layer in healthy placentas and is largely absent in preeclampsia." (PMID 41416997, 2025). "Extending these investigations to identify the precise role and targets of HDAC9 within specific placenta cell types as well as the upstream regulators responsible for disrupted HDAC9 in preeclampsia may provide unique perspectives in the field." (PMID 41416997, 2025).
preeclampsia (continued). "Thus, it is plausible that aberrant kinase activity downstream of AT1 and endothelin-1 receptor activation contributes to reduced nuclear HDAC9 in preeclampsia, potentially altering gene expression programs critical for placental function." (PMID 41416997, 2025). "Integrating newfound evidence from preeclampsia-focused studies with those of other disease models reveals a complex interplay between HDACs and relevant signaling pathways, which may control the activity of HDAC9 and its regulation of downstream targets." (PMID 41416997, 2025). "Given that HDAC9 promotes both NF-κB and NLRP3 inflammasome activation in macrophages, its dysregulation may amplify these inflammatory cascades in preeclampsia." (PMID 41416997, 2025). "As mentioned, HDAC9 alters the acetylation status of FOXO1, promoting its activation; therefore, some deleterious cellular complications in preeclampsia may be a consequence of FOXO1 dysregulation secondary to the loss of HDAC9." (PMID 41416997, 2025). "HDAC9 does not have an obvious role in the control of this particular GPCR pathway in preeclampsia except for its implications in the regulation of RGS2, which can also act on Gαi." (PMID 41416997, 2025). "Although the role of HDAC9 in modulating immunity and inflammation has not been defined in pregnancy or preeclampsia, evidence from related models suggests that HDAC9 primarily regulates innate immune responses, with limited evidence pointing to potential effects on adaptive immunity." (PMID 41416997, 2025). "HDAC9 has emerged as an underlying contributor via its control of regulator of G-protein signaling (RGS) proteins that dampen GPCR activation, and GPCR kinases may also affect the localization of HDAC9, creating an amplified feedback loop that reinforces excessive GPCR signaling in preeclampsia." (PMID 41416997, 2025).
thymic carcinoma (3 papers, 2017 to 2023). Thymic carcinoma (TC) is a type of thymic epithelial neoplasm characterized by a high malignant potential. "Therefore, the HDAC inhibitors targeting HDAC9 could be a promising treatment option for inoperable thymic carcinomas if the relevant role of HDAC9 in TECs and TETs, especially in the neuroendocrine lineage, is clarified." (PMID 38201543, 2023). "Moreover, the selective upregulation of HDAC9 in thymic carcinomas compared to thymomas implies that thymic carcinomas may strongly rely on HDAC9 for survival." (PMID 38201543, 2023). "As a result, further in vitro and in vivo studies are necessary to validate our findings, particularly those related to the activation of HDAC9 and NFATC1 in thymic carcinomas, before they can be applied in a clinical context." (PMID 38201543, 2023). "When exploring the possible regulators of this phenotype, we discovered that HDAC9 and NFATC1 were characteristically expressed in the neuroendocrine group in adult TECs and thymic carcinomas." (PMID 38201543, 2023). "Furthermore, HIPK2, HDAC9, and FEZF2 displayed a significantly higher expression in thymic carcinomas than in thymomas in both datasets." (PMID 38201543, 2023). "Therefore, we investigated the correlation between methylation and mRNA expression status in the genes newly identified as activated or suppressed in thymic carcinomas, specifically HIPK2, HDAC9, NFATC1, PAX9, and SIX1 (the methylation status of FEZF2 was not available in the dataset)." (PMID 38201543, 2023). "HDAC9 and NFATC1, which were characteristically expressed in the neuroendocrine group in adult TECs and thymic carcinomas, should be investigated further due to their potential biological significance in TECs and their possibility of being therapeutic targets of thymic carcinomas." (PMID 38201543, 2023).
calcification (2 papers, 2021 to 2024). Process by which organic tissue becomes hardened by the physiologic deposit of calcium salts. "It is worth emphasizing that HDAC9 influences phenotypic characteristics of vascular smooth muscle cells and is connected to atherosclerotic aortic calcification, and BHB is able to downregulate HDAC9 to suppress vascular calcification." (PMID 39075604, 2024).
coronary atherosclerosis (2 papers, 2016 to 2024). Atherosclerosis of the coronary vasculature. "As a genetic variant in HDAC9 gene, rs2107595 is closely associated with the severity of coronary atherosclerosis in a Chinese Han population." (PMID 39698913, 2024). "Taken together, our data suggest that SNP rs2107595 may contribute to coronary atherosclerosis and CAD risk through a possible mechanism of regulating HDAC9 expression and gene-environment interactions." (PMID 27494404, 2016). "Taking all these findings together, we hypothesize that SNP rs2107595 may also contribute to the development of coronary atherosclerosis and CAD risk by modifying HDAC9 expression." (PMID 27494404, 2016).
craniosynostosis (2 papers, 2022 to 2023). Craniosynostosis is defined as the premature fusion of one or more cranial sutures leading to secondary distortion of skull shape resulting in skull deformities with a variable presentation. "They showed that craniosynostosis patients with SVs containing the Histone deacetylase 9 (HDAC9) protein-coding sequence are associated with disruption of TWIST1 regulatory elements that reside within the HDAC9 sequence." (PMID 35205324, 2022). "Deletions in HDAC9 gene, but not in the TWIST1 protein-coding sequence, caused development of craniosynostosis." (PMID 36795294, 2023).
Hypercholesterolemia (2 papers, 2016 to 2023). An increased concentration of cholesterol in the blood.
male pattern baldness (2 papers, 2013 to 2017). "In a recent GWAS study HDAC9 was found to be associated with male pattern baldness." (PMID 23627667, 2013). "After extensive simulation studies we investigated three real life scenarios: First, the interplay between androgen receptor (AR) and HDAC9 in the context of male pattern baldness." (PMID 23627667, 2013).
Osteopenia (2 papers, 2017 to 2019). Osteopenia is a term to define bone density that is not normal but also not as low as osteoporosis. "Deletion of either Hdac7 or Hdac9 in BMMs resulted in enhanced osteoclast differentiation in vitro, and increased bone resorption and osteopenia in mice in vivo." (PMID 28953929, 2017).
splenic marginal zone lymphoma (2 papers, 2014 to 2016). Splenic marginal zone lymphoma is a rare, indolent B-cell non-Hodgkin lymphoma characterized by abnormal clonal proliferation of mature B-lymphocytes with involvement in the spleen, bone marrow and, frequently, the blood. "Here, we report that the Eμ-HDAC9 GEM model develops splenic marginal zone lymphoma and lymphoproliferative disease (LPD) with progression towards aggressive DLBCL, with gene expression profiling supporting a germinal center cell origin, as is also seen in human B-NHL tumors." (PMID 27799148, 2016).
acute coronary syndrome (1 paper, 2016). Signs and symptoms related to acute ischemia of the myocardium secondary to coronary artery disease. "However, whether HDAC9 gene is associated with an increased susceptibility to acute coronary syndrome (ACS) in Chinese Han population is not known." (PMID 27642596, 2016).
endometrioid carcinoma (1 paper, 2022). "HDAC9 was overexpressed in our TMA SC samples and in endometrioid carcinoma samples of TCGA dataset." (PMID 35226658, 2022).
intervertebral disc degeneration (1 paper, 2023). "Histone deacetylase 9 (HDAC9) was dramatically decreased in the degenerative nucleus pulposus (NP) samples of patients with intervertebral disc degeneration (IVDD) according to bioinformatics analysis of Gene Expression Omnibus (GEO) GSE56081 dataset." (PMID 38093179, 2023).
primary biliary cirrhosis (1 paper, 2020). "HDAC9 expression is also markedly higher in diseased human livers, including primary biliary cirrhosis (PBC), alcoholic cirrhosis and NASH." (PMID 33086678, 2020).
Splenomegaly (1 paper, 2016). Abnormal increased size of the spleen. "When analyzed between 6 and 12 months of age, a fraction (3/17, 18%) of Eμ-HDAC9 mice exhibited splenomegaly, compared to 0/10 wild-type littermates." (PMID 27799148, 2016).
status epilepticus (1 paper, 2016). Status epilepticus is defined as a continuous seizure lasting more than 30 min, or two or more seizures without full recovery of consciousness between any of them. "Six to 12 h after induction of the status epilepticus HDAC9 mRNA levels declined even further (statistically not significant)." (PMID 26603269, 2016).
cancer (2,245 papers, 2005 to 2026). A tumor composed of atypical neoplastic, often pleomorphic cells that invade other tissues. "Future studies should, therefore, focus on gaining deeper insight into the mechanisms underlying HDAC9-associated activities in individual types of cancer." (PMID 34318404, 2021). "HDAC7 seems to play an important role for bone development and in diabetes, while a flurry of recent articles have similarly associated HDAC9 with several disease pathways including various cancers and stroke." (PMID 31351464, 2019). "While none of these proteins was found to be mutated in BRM-deficient cancer cell lines, HDAC9 and GATA3 were overexpressed in both lung cancer-derived cell lines and primary lung tumors, as well as in rhabdoid cell lines and primary tumors." (PMID 25774356, 2014). "Identifying the domain of CAGEs that is necessary for binding to HDAC9 may help to understand the mechanisms associated with CAGE-promoted anti-cancer drug resistance." (PMID 38920983, 2024). "Notably, mutations in HDACs, like HDAC2, HDAC4 and HDAC9, have been identified in various cancers (colon, breast, and prostate cancer)." (PMID 38794190, 2024). "Similarly, according to several research findings, HDAC9 has been implicated in the development of malignant tumors." (PMID 35865469, 2022). "Overall, dysregulated HDAC9 expression has been linked to a variety of cancers." (PMID 34318404, 2021). "HDAC9 has been also implicated in DNA repair, a poorly investigated HDAC9-function that could be relevant in cancer progression." (PMID 33513699, 2021). "Higher expression of HDAC9 has been associated with poor prognosis in different cancer types." (PMID 34312479, 2021). "Mutation or aberrant expression of HDAC9 has been implicated in diverse conditions, including ischemic stroke, schizophrenia and obesity, and also as a maker of poor outcome in cancer." (PMID 27799148, 2016). "In this study, we demonstrated that SNP rs10248565 in HDAC9 may be a potential biomarker for identifying important genetic determinants of cancer susceptibility and elucidating the genetic etiology of lung cancer in non-smoking females." (PMID 24650256, 2014). "The findings of this study show that chronic arsenic exposure induces the upregulation of well-known transcription factors associated with cancer stem cell (CSC) phenotypes, including OCT2, CD133, ALDH1, and HDAC9." (PMID 40368219, 2025). "The roles of CAGEs, HDAC9, and miR-512 in in vivo anti-cancer drug resistance of AGSR cells also merit further study." (PMID 38920983, 2024). "HDAC9 is frequently overexpressed in cancer cells, rendering it a significant target in cancer therapy research." (PMID 38932355, 2024). "Our results can contribute to the understanding of the molecular roles of HDAC9 in anti-cancer drug resistance." (PMID 38920983, 2024). "AGSR cells with an anti-cancer drug-resistant phenotype showed higher levels of CAGEs and HDAC9 than normal AGS cells." (PMID 38920983, 2024). "It is also necessary to identify the domain of HDAC9 that is necessary for conferring resistance to anti-cancer drugs." (PMID 38920983, 2024). "This study aimed to investigate the relationship between CAGEs and HDAC9 in relation to anti-cancer drug resistance." (PMID 38920983, 2024). "HDAC9 is important in the human physiological system and is involved in the development of various diseases, such as cancer, diabetes, atherosclerosis, cardiovascular diseases, and liver fibrosis." (PMID 39193364, 2024). "HDAC9 has also been reported to affect the prognosis of various cancers by accelerating cell proliferation and blocking cell apoptosis." (PMID 37250142, 2023). "HDAC9 is a member of the histone deacetylase (HDAC) family, involved in transcriptional regulation, cell death, and especially in carcinogenesis and cancer progression." (PMID 36619866, 2022).